CLEC18C (C-type lectin domain family 18 member C)
Description:
Binds polysaccharidesin a Ca(2+)-independent manner with a preferentially binding to fucoidan, beta-glucans and galactans.
Synonyms: MGC34761; MRCL; MRCL3
Tractability: Antibody: UniProt places it where antibodies can reach, with medium confidence; UniProt predicts a signal peptide or a membrane-spanning region; its Gene Ontology location is reachable by antibodies, with medium confidence.
Gene: Protein-coding gene on chromosome 16 (70,173,322 to 70,187,361, forward strand). Ensembl gene ENSG00000157335.
Subcellular location: Secreted; Endoplasmic reticulum; Golgi apparatus; Endosome
Gene Ontology:
Molecular function: polysaccharide binding
Cellular component: endoplasmic reticulum; endosome; extracellular region; Golgi apparatus
Genetic constraint (gnomAD): Loss-of-function variants: 2 observed, 11.91 expected, observed/expected ratio (o/e) 0.17, 90% interval 0.068 to 0.53. The synonymous counts are far from expectation, so gnomAD's model fits this gene poorly and the ratio says little. Missense variants: 25 observed, 124.98 expected, observed/expected ratio (o/e) 0.2, 90% interval 0.14 to 0.28. Synonymous variants: 13 observed, 47.57 expected, observed/expected ratio (o/e) 0.27, 90% interval 0.18 to 0.44.
Homologues: Orthologues: macaque CLEC18A (96% identical), dog CLEC18C (80% identical), rat Clec18a (78% identical), mouse Clec18a (75% identical), Drosophila melanogaster CG42564 (18% identical), Caenorhabditis elegans scl-23 (15% identical), Caenorhabditis elegans scl-5 (13% identical), Caenorhabditis elegans scl-14 (12% identical), Caenorhabditis elegans scl-10 (12% identical), Caenorhabditis elegans scl-20 (12% identical), Drosophila melanogaster CG8483 (12% identical), Caenorhabditis elegans scl-12 (12% identical), and 36 more. Paralogues in human: CLEC18A (99% identical), CLEC18B (99% identical), CRISPLD2 (23% identical), CRISPLD1 (22% identical), CRISP1 (17% identical), CRISP3 (17% identical), CRISP2 (16% identical), R3HDML (16% identical), PI15 (15% identical), GLIPR1L1 (15% identical), GLIPR1L2 (14% identical), GLIPR1 (14% identical), and 1 more.
Diseases named in the same sentence as CLEC18C in open-access papers:
CLEC18C is named in the same sentence as 1 disease in open-access papers, as found by Europe PMC text mining. Sharing a sentence is not in itself a finding about the gene and the disease.
CLEC18C shares sentences with these, for which no sentence is quoted: dengue (1 paper).